CARS2 (cysteinyl-tRNA synthetase 2, mitochondrial)
Description:
Mitochondrial cysteine-specific aminoacyl-tRNA synthetase that catalyzes the ATP-dependent ligation of cysteine to tRNA(Cys). In addition to its role as an aminoacyl-tRNA synthetase, has also cysteine persulfide synthase activity. Produces reactive persulfide species such as cysteine persulfide (CysSSH) from substrate cysteine and mediate direct incorporation of CysSSH into proteins during translations, resulting in protein persulfides and polysulfides. CysSSHs behave as potent antioxidants and cellular protectants.
Synonyms: CysRS; FLJ12118; COXPD27
Tractability: PROTAC: ubiquitination databases record sites on it; its protein half-life has been measured.
Gene: Protein-coding gene on chromosome 13 (110,641,411 to 110,713,603, reverse strand). Ensembl gene ENSG00000134905.
Subcellular location: Mitochondrion
Subcellular location (Human Protein Atlas): Mitochondria; Nucleoplasm
Pathways (Reactome):
Metabolism of proteins: Mitochondrial tRNA aminoacylation
Gene Ontology:
Molecular function: cysteine-tRNA ligase activity; aminoacyl-tRNA ligase activity; ATP binding; nucleotide binding
Biological process: cysteinyl-tRNA aminoacylation; tRNA aminoacylation for protein translation
Cellular component: mitochondrion
Genetic constraint (gnomAD): Loss-of-function variants: 40 observed, 42.51 expected, observed/expected ratio (o/e) 0.94, 90% interval 0.73 to 1.23. The upper end of that interval is the gene's LOEUF score, 1.23, which puts it in group 5 of 6, group 1 being the genes least tolerant of losing a copy. Missense variants: 660 observed, 588.67 expected, observed/expected ratio (o/e) 1.12, 90% interval 1.05 to 1.2. Synonymous variants: 278 observed, 238.19 expected, observed/expected ratio (o/e) 1.17, 90% interval 1.06 to 1.29.
Gene-disease validity (ClinGen):
ClinGen rates the evidence that CARS2 causes each of these diseases.
mitochondrial disease (autosomal recessive): Moderate.
Homologues: Orthologues: chimpanzee CARS2 (98% identical), macaque CARS2 (94% identical), dog CARS2 (79% identical), mouse Cars2 (77% identical), guinea pig CARS2 (75% identical), rat Cars2 (74% identical), pig CARS2 (74% identical), tropical clawed frog cars2 (57% identical), zebrafish cars2 (55% identical), Drosophila melanogaster CysRS-m (38% identical). Paralogues in human: CARS1 (38% identical).
Diseases named in the same sentence as CARS2 in open-access papers:
CARS2 is named in the same sentence as 43 diseases in open-access papers, as found by Europe PMC text mining. Sharing a sentence is not in itself a finding about the gene and the disease. The quoted sentences say what the papers report.
epilepsy (4 papers, 2023 to 2025). A brain disorder characterized by episodes of abnormally increased neuronal discharge resulting in transient episodes of sensory or motor neurological dysfunction, or psychic dysfunction. "In addition, polymorphisms of GRIK2 were associated with an increased risk of epilepsy in children, while polymorphisms of CARS2 were associated with severe progressive myoclonic epilepsy and mitochondria-related diseases." (PMID 40843195, 2025).
colorectal cancer (3 papers, 2021 to 2023). A primary or metastatic malignant neoplasm that affects the colon or rectum. "For example, these canonical enzymes and Cars2 are known to be highly expressed in cancer tissues such as human Basal-like breast cancers and colorectal cancer tissues." (PMID 37107243, 2023). "MUC12 is associated with Tn polyagglutination syndrome and colorectal cancer and previous GWAS have pointed out the effect of the genetic variants in MUC12 on hemoglobin levels and CARS2 on diastolic blood pressure." (PMID 34064523, 2021).
Progressive myoclonic epilepsy (3 papers, 2019 to 2025). "It was found that mutations in CARS2 are associated with progressive myoclonus epilepsy and could lead to a severe epileptic encephalopathy and complex movement disorder." (PMID 34064523, 2021).
viral infection (2 papers, 2023 to 2025). "Supersulfides have been shown to play an important role in COPD using CARS2 heterozygous knockout mice subjected to viral infection (e.g., SARS-CoV-2) or elastase treatment." (PMID 40001475, 2025). "The viral infection model was characterized by a marked increase in 8-OHdG and pro-inflammatory cytokines in CARS2 heterozygous knockout mice compared with wild-type mice." (PMID 40001475, 2025). "The viral infection affected Cars2+/− mice more extensively than did WT mice in terms of lung tissue damage and lethality, as well as inflammatory changes in the infected lungs, as assessed by pathological examinations and survival rate analysis." (PMID 37491435, 2023).
Alpers syndrome (1 paper, 2021). A cerebral degeneration that results in progressive degeneration of grey matter in the cerebrum and has_symptom convulsions. "Variants in PARS2, CARS2, GABRB2, FARS2, and NARS2 were also reported in Alpers’ syndrome patients." (PMID 34690748, 2021). "In recent years, with the advancement of genetic testing technology, Alpers syndrome caused by NON-POLG genes has also been continuously reported, including mitochondrial aminoacyl transfer RNA synthetase related genes (PARS2, CARS2, FARS2 and NARS2) and γ-GABA receptor related genes Gene (GABRB2)." (PMID 34690748, 2021).
chronic lung disease (1 paper, 2023). According to the definitions of the American and British Thoracic Societies, including pulmonary functional tests, X-rays, and CT scans for items such as fibrosis, bronchiectasis, bullae, emphysema, nodular or lymphomatous abnormalities. "We thus showed that CARS2/CPERS is the major contributor to supersulphide biosynthesis in the lungs, and has host defense and protective functions in respiratory viral infections and chronic lung diseases such as COPD and IPF." (PMID 37491435, 2023).
chronic obstructive pulmonary disease (1 paper, 2025). A chronic and progressive lung disorder characterized by the loss of elasticity of the bronchial tree and the air sacs, destruction of the air sacs wall, thickening of the bronchial wall, and mucous accumulation in the bronchial tree. "We further demonstrated that Cars2+/- mice exhibit severe symptoms of chronic obstructive pulmonary disease (COPD)." (PMID 40303402, 2025).
cognitive decline (1 paper, 2023). "Though, the variant is lying in the less conserved region of CARS2 protein but has been previously linked to severe myoclonic epilepsy, progressive spastic tetraparesis, vision and hearing impairment, and cognitive decline." (PMID 37359369, 2023).
colitis (1 paper, 2025). Inflammation of the colon. "Treatment with GSSSG significantly ameliorated body weight reduction and histological colitis induced by Cars2+/- naïve CD4+ T cell transfer." (PMID 40303402, 2025). "Rag2-/- hosts that received Cars2+/- versus WT CD4+ T cells exhibited severer body weight loss and histological colitis." (PMID 40303402, 2025). "Based on previous findings demonstrating a correlation between the degree of homeostatic proliferation of CD4+ T cells and severity of colitis, we hypothesized that enhanced homeostatic proliferation of Cars2+/- naive CD4+ T cells can exacerbate colitis in certain circumstances." (PMID 40303402, 2025). "Indeed, CD4+ T cells with reduced levels of CARS2/CPERS exhibited accelerated cell cycle entry and induced severer colitis in Rag2-/- mice, and treatment with GSSSG, an endogenous donor of supersulfide that is generated by CARS2/CPERS, ameliorated inflammation." (PMID 40303402, 2025). "GSSSG administration ameliorated colitis induced by Cars2+/- but not WT CD4+ T cells." (PMID 40303402, 2025).
diffuse large B-cell lymphoma (1 paper, 2020). "Diffuse large B-cell lymphoma (DLBC) overexpresses all the synthetases compared to normal tissues (except for CARS2), which may be partially enabled by gene amplifications at the DNA level." (PMID 33266490, 2020).
emphysema (1 paper, 2023). "Similarly, the same GSSSG treatment reduced CSExt-induced emphysema and its associated cellular senescence in lungs of both WT and Cars2+/− mice." (PMID 37491435, 2023). "In addition, development of emphysema was enhanced in lungs in Cars2+/− mice compared with that in WT mouse lungs, as confirmed by measuring the mean linear intercept and LAV/TLV determined by means of a 3D micro-CT morphometric image." (PMID 37491435, 2023).
influenza infection (1 paper, 2023). "Endogenous formation supersulphides (e.g., CysSSH, GSSH, HSH, and HSSH) in lungs was found to be lower in Cars2+/− mice than in WT mice especially before (day 0) influenza infection." (PMID 37491435, 2023). "For example, we found that influenza infection increased various biomarkers of oxidative (nitrative) stress, which include 8-hydroxy-2ʹ-deoxyguanosine (8-OHdG), GSSG/GSH ratio (GSSG/GSH), 3-nitrotyrosine (3-NT) formation in Cars2+/− mice after infection." (PMID 37491435, 2023).
lung fibrosis (1 paper, 2023). "Cars2+/− mice treated with bleomycin, compared with WT mice treated with bleomycin, showed increased body weight loss and worsened lung fibrosis as evaluated by 3D morphometric analysis with micro-CT." (PMID 37491435, 2023).
osteoarthritis (1 paper, 2025). A noninflammatory degenerative joint disease occurring chiefly in older persons, characterized by degeneration of the articular cartilage, hypertrophy of bone at the margins and changes in the synovial membrane. "Using Cars2AINK/+ mutant mice, in which the KIIK motif of CARS2 essential for supersulfide production was replaced with AINK, we evaluated the role of supersulfides in fracture healing and cartilage homeostasis during osteoarthritis (OA)." (PMID 39983344, 2025).
ovarian carcinoma (1 paper, 2021). A malignant neoplasm originating from the surface ovarian epithelium. "Of the genes implicated by the other novel SNP loci, CARS2 is associated with combined oxidative phosphorylation deficiency and ovarian cancer." (PMID 34064523, 2021).
cancer (6 papers, 2020 to 2025). A tumor composed of atypical neoplastic, often pleomorphic cells that invade other tissues. "Through multi-omics and pan-cancer analyses, CARS2, NFU1, and SYNJ1 were identified as hub genes to construct LRGS and regulate the lactate-related TME in HNSCC." (PMID 39991576, 2025). "In pan-cancer analysis, CARS2 acted as an oncogene in HNSCC, kidney renal clear cell carcinoma, liver hepatocellular carcinoma, and SKCM." (PMID 39991576, 2025). "While the regulation of CBS, CSE, 3-MST (and to a lesser degree CARS2) in various forms of cancer has been studied intensively, the regulation of the various H2S degradation pathways remains to be investigated." (PMID 39643979, 2024). "These interactions further underscore the multifaceted nature of CARS2 and its potential as a therapeutic target in cancers such as HCC, CRC, and basal-like breast cancer (BLBC)." (PMID 39643979, 2024). "The mechanism by which CARS2-mediated H2S production contributes to various aspects of cancer biology, including cell proliferation and migration, is poorly understood and requires further investigation." (PMID 39643979, 2024). "No other studies have confirmed the relationship between SEC61G, CARS2, and cancer, so it is worth further in-depth study." (PMID 33959617, 2021). "TARS1, VARS1, CARS2, DARS2, and YARS2 are associated with unfavorable outcomes in two cancer types." (PMID 33266490, 2020). "However, few studies have focused on the role of CARS2 in cancer development." (PMID 39991576, 2025). "Apoptosis (e.g., BID, CASP6, etc.)and aminoacyl-tRNA biosynthesis (e.g., CARS2 and AARS2) were predominant in the D4 (HGIN stage), suggesting cancer malignancy." (PMID 36991000, 2023). "There are a few aaRSs that are downregulated in multiple cancer types, including HARS2 (n = 6), WARS1 (n = 4), CARS2 (n = 4), IARS1 (n = 3), RARS2 (n = 3), VARS2 (n = 3), and AIMP3/EEF1E1 (n = 3), suggesting these aaRSs may possess certain specific cancer-inhibiting roles." (PMID 33266490, 2020).
infection (2 papers, 2023 to 2025). The state of being infected such as from the introduction of a foreign agent such as serum, vaccine, antigenic substance or organism. "Interestingly, transcription of genes relating to mitochondrial functions (e.g., IFI27L2a, RPS21, CARS2) were markedly upregulated only during the per-acute phase of infection (1–3 dpi), but not in 4–6 dpi." (PMID 40758745, 2025).
genetic disorders (1 paper, 2019). "However, some genetic disorders are extremely rare (eg, CARS2), and those phenotypes are likely to be expanded in the coming years." (PMID 31584223, 2019).
inflammation (1 paper, 2025). Aberrant reaction of the microcirculation characterized by movement of fluid and leukocytes from the blood into extravascular tissues. "Since we recently found that exogenous administration of GSSSG inhibits TCR signaling and protects allergen-induced airway inflammation, reduction of CARS2/CPERS expression in CD4+ T cells may enhance homeostatic proliferation via augmented TCR signaling." (PMID 40303402, 2025).
metabolic disease (1 paper, 2025). A congenital disorder (due to inherited enzyme abnormality) or acquired (due to failure of a metabolically important organ) disorder resulting from an abnormal metabolic process. "Notably, movement disorders are often associated with metabolic diseases and have been described in conditions related to deficiencies in other aminoacyl-tRNA synthetases, including WARS2, CARS2, PARS2, RARS2, and AARS2." (PMID 41002930, 2025).
neurological disorders (1 paper, 2017). "Although the patient’s clinical symptoms resulted from loss of a canonical function of CARS2, which the neurological disorders might be caused by impairment of CPERS activity of CARS2 is plausible, and thus this impaired activity may overlap with the observed impairment of Cys-tRNA aminoacylation." (PMID 29079736, 2017).
CARS2 also shares sentences with these, for which no sentence is quoted: Epileptic encephalopathy (2 papers); breast carcinoma (1); childhood onset epileptic encephalopathy (1); Dystonia (1); hypogonadotropic hypogonadism (1); Immunodeficiency (1); infantile spasms (1); Leigh syndrome (1); leukodystrophies (1); lymphopenia (1); MERRF syndrome (1); microcephaly (1); movement disorder (1); myoclonic epilepsy (1); ovarian failure (1); Parkinson disease (1); schizophrenia (1); sensorineural hearing loss with (1); Spastic tetraparesis (1); tumor (1); type 2 diabetes (1); viral pneumonia (1).